IL4R (interleukin 4 receptor)
Diseases named in the same sentence as IL4R in open-access papers (continued):
Sharing a sentence is not in itself a finding about the gene and the disease.
age-related hearing loss (1 paper, 2022). "Il4r encodes the interleukin-4 receptor, which has been associated with age-related hearing loss in a genetic population study." (PMID 35454087, 2022).
alexithymia (1 paper, 2024). An agnosia that is a deficiency in understanding, processing, or describing emotions. "In addition, in patients with alexithymia, anti–IL-4Rα improves clinical symptoms of AD, such as itching, and QoL more than in patients without alexithymia." (PMID 38035127, 2024). "Infact, in both patients with alexithymia and without alexithymia, treatment with anti–IL-4Rα improves psychological burden in patients with AD." (PMID 38035127, 2024). "In summary, to our knowledge, our study for the first time shows that the treatment with anti–IL-4Rα for AD reduces the prevalence of psychological burden in both patients with alexithymia and without alexithymia." (PMID 38035127, 2024). "However, in our study, the presence of alexithymia did not affect the effectiveness of treatment with anti–IL-4Rα." (PMID 38035127, 2024). "Probably, because patients with alexithymia had a greater severity of the disease at the baseline than patients without alexithymia (EASI = 30.85 vs 23.50), treatment with anti–IL-4Rα for 16 weeks was most effective for them in reducing itching, and this positively affected their QoL." (PMID 38035127, 2024).
allergic conjunctivitis (1 paper, 2023). "Together, these data suggest that an IL-4Rα/basophil axis plays a role in the development of murine allergic conjunctivitis." (PMID 36626228, 2023).
aspergillosis (1 paper, 2022). Aspergillosis is an infection, growth, or allergic response caused by the Aspergillus fungus. "Therefore, polymorphisms of many immune-related genes are associated with susceptibility to aspergillosis, such as tumor necrosis factor receptor 1 (TNFR1), TLR1/4/5/6, Dectin-1, DC-SIGN, IL-8, IL-10, IL-12, IL-4R, IFN-γ, IRF4 and so on." (PMID 35407478, 2022).
autoimmune encephalitis (1 paper, 2021). Inflammation of the brain secondary to an immune response triggered by the body itself. "Similarly, in experimental autoimmune encephalitis models, externally administered IL-4 has been shown to improve axonal damage via IL-4 receptor (IL-4R)-mediated signaling pathway." (PMID 33504893, 2021).
autoimmune hepatitis (1 paper, 2015). Hepatitis caused by autoantibodies. "Among validated proteins, IL4 receptor autoantigen was studied for the neutralization role in autoimmune hepatitis, demonstrating that IL4R autoantibodies are functional in autoimmune hepatitis disease." (PMID 26375394, 2015).
Autoimmunity (1 paper, 2022). The occurrence of an immune reaction against the organism's own cells or tissues. "During an antigen rechallenge, rapid production of IL-4 occurs, which causes apoptosis of neonatal Th1 cells through the formation of heteroreceptor IL-4Rα/IL-13Rα1, which together with regulatory T cells takes part in the control over peripheral tolerance and restrains autoimmunity in adults." (PMID 36619667, 2022).
B cell lymphoma (1 paper, 2024). "The function of IL4/IL4R may be to accelerate AITL progression and trigger the transition from AITL to B cell lymphoma, indicating that IL4/IL4R is a potential pharmacological target." (PMID 38145335, 2024).
biliary tract cancer (1 paper, 2014). "Here, we evaluated the antitumor activity of the IL-4Rα-lytic hybrid peptide as a novel molecular targeted therapy for human biliary tract cancer (BTC)." (PMID 24868471, 2014).
bladder tumor (1 paper, 2014). "Thus, IL-4Rα may be a bladder tumor-associated protein and a prognostic biomarker." (PMID 25208941, 2014). "As it was not known whether human BC expressed IL-4R, we examined the expression of these receptors in cell lines and pathological samples for their potential role as bladder tumor-associated protein." (PMID 25208941, 2014).
brain inflammation (1 paper, 2007). "Since IL-4 induces apoptosis in activated glial cells that express IL-4R, IL-4 may contribute to the down-regulation of brain inflammation in CM-R mice." (PMID 18062806, 2007).
cardiac sarcoidosis (1 paper, 2025). Sarcoidosis affecting the tissues of the heart. "The increased expression of CSF1R, IL7R, and IL4R in macrophages, together with the activation of their signaling cascades, suggests a critical role for these receptors in the pathogenesis of cardiac sarcoidosis." (PMID 40521183, 2025).
Chagas disease (1 paper, 2018). A parasitic infection caused by Trypanosoma cruzi. "So far, most studies addressing the function of IL-4Rα-mediated signaling in experimental Chagas disease employed IL-4-deficient(−/−) and STAT6−/− mice or neutralization of IL-4 by administration of monoclonal antibodies." (PMID 30555475, 2018). "Because this arginase inhibition resulted in a decreased susceptibility to experimental Chagas disease our study supports in summary the conclusion that IL-13/IL-4Rα-driven Arg-1 expression contributes to the permissiveness of the host to T. cruzi infection." (PMID 30555475, 2018). "The poor expression of IL-4 and IL-13 after experimental infection of wildtype mice with T. cruzi nearly exclude a reasonable analysis of the contribution of the IL-4Rα-Arg-1 pathway in susceptibility to experimental Chagas disease." (PMID 30555475, 2018). "In summary, we here give evidence that IL-4Rα-induced Arg-1 mediates susceptibility to acute experimental Chagas disease by several - mutually not exclusive - mechanisms downstream of Arg-1 including L-arginine depletion in MDSCs and AAM and polyamine synthesis." (PMID 30555475, 2018).
cholangiocarcinoma (1 paper, 2014). A carcinoma that arises from the intrahepatic biliary tree (intrahepatic cholangiocarcinoma) or from the junction, or adjacent to the junction, of the right and left hepatic ducts (hilar cholangiocarcinoma). "The expression levels of IL-4Rα protein were the highest in intrahepatic cholangiocarcinoma cell lines (CCKS-1 and KKU-100) among tested cell lines." (PMID 24868471, 2014).
choroidal neovascularization (1 paper, 2020). An eye disorder described by the growth of new blood vessels that originate from the choroid through a break in the Bruch membrane into the sub–retinal pigment epithelium (sub-RPE) or subretinal space. "Requirements of IL-4/IL-4Rα in the inductive phase of choroidal neovascularization (CNV)." (PMID 32366355, 2020).
chronic asthma (1 paper, 2023). An asthma that is characterized by the development of persistent airway inflammation and recurrent attacks of breathlessness and wheezing, which vary in severity and frequency. "We hypothesized that further evidence for the contribution of excessive IL4R being associated with CRC progression could be seen in medical records, and specifically that chronic asthma patients were more likely to be diagnosed with metastatic CRC." (PMID 37860183, 2023).
clear cell carcinoma (1 paper, 2025). "Owing to the rarity of clear cell carcinoma and the limited availability of clinical cases, the roles of NR1H4 and IL4R in OCCC and their associations with immune cell infiltration require further validation through prospective studies with larger sample sizes." (PMID 40656893, 2025).
coccidioidomycosis (1 paper, 2026). A fungal infection caused by Coccidioides immitis. "Our findings give a mechanistic rationale for blockade of IL4R in Th2-skewed patients with refractory coccidioidomycosis." (PMID 42012883, 2026).
colonic adenomas (1 paper, 2013). "We did demonstrate that a lack of IL-4Rα-mediated signalling is associated with less nuclear and cytoplasmic β-catenin staining in epithelial cells in colonic adenomas." (PMID 23784081, 2013).
colorectal tumour (1 paper, 2013). "We noted that IL-4Rα−/− mice failed to generate a CD11b+ Gr1+ MDSC response to colorectal tumours, consistent with the existing literature." (PMID 23784081, 2013). "However, the small size of AOM-induced colorectal tumours did not allow us to investigate whether IL-4Rα−/− tumours contained less MDSCs and CD8+ lymphocytes by flow cytometry in keeping with this hypothesis." (PMID 23784081, 2013).
cysticercosis (1 paper, 2024). "Our data have revealed a crucial role for IL-4Rα in developing susceptibility during murine cysticercosis, which is associated with M2 macrophages." (PMID 38392907, 2024). "Hence, we are interested in demonstrating the influence of IL-4Rα in developing and maintaining alternatively activated macrophages (AAMs or M2) and its role in the outcome of murine cysticercosis caused by the cestode T. crassiceps." (PMID 38392907, 2024). "Interestingly, our new results suggest that the resistance to cysticercosis observed in cre/loxP mice is mediated by the absence of suppressive M2 response, which is IL-4Rα dependent." (PMID 38392907, 2024).
DEB pruriginosa (1 paper, 2025). "Efficacy of the anti-IL-4R-alfa monoclonal antibody dupilumab has been recently described in several patients, in particular affected by DEB pruriginosa." (PMID 40091088, 2025).
dengue (1 paper, 2023). "Polymorphisms in the IL4R and IL6R cytokine receptors were also pinpointed as risk factors for clinical dengue in Colombian children, as these may introduce changes in the T cells signal transduction, and thus alter the activation of Th subtypes in dengue." (PMID 38076464, 2023).
dilated cardiomyopathy (1 paper, 2017). Cardiomyopathy which is characterized by dilation and contractile dysfunction of the left and right ventricles. "Remarkably, the expression of the chains comprising type‐2 IL‐4R, Il13ra1 and Il4ra were downregulated in the failing hearts of patients with ischemic and dilated cardiomyopathy, compared with controls." (PMID 28528324, 2017).
endotoxemia (1 paper, 2013). "Indeed IL-4Rα LysCre mice, which are deficient in IL-4Rα specifically on macrophages and neutrophils, do not develop M2 macrophages and following S. mansoni infections there is endotoxemia and mortality of all infected mice." (PMID 23596444, 2013).
esophageal cancer (1 paper, 2020). A primary or metastatic malignant neoplasm involving the esophagus. "The presence of IL-4Rα protein has previously been demonstrated in the majority of investigated colonic and gastric tumors but data concerning esophageal cancer are scarce." (PMID 32512917, 2020).
Fever (1 paper, 2006). Body temperature elevated above the normal range. "Hay fever cases exhibiting IL4R Q576R GG, IL10(-819) TT or IL18(-137) CC genotype had also increased total IgE levels, although not significant due to low statistically power." (PMID 16759385, 2006).
filariasis (1 paper, 2020). "Beyond basic immunobiology, the identification of eosinophilic control of patent adult B. malayi infection and its successful manipulation by compound IL-4Rα−/−CCR3−/− or IL-4Rα−/−IL-5−/− deficiencies offers new selective knockout research models for translational filariasis research." (PMID 32571840, 2020).
glomerular diseases (1 paper, 2023). "Antibody-mediated depletion of TNF-α, IL-6, and IL-4Rα after common cold model induction in BALB/cJ mice resulted in a significant decline in albuminuria, suggesting potential therapeutic avenues for treating relapse of primary glomerular diseases after a common cold." (PMID 37040185, 2023).
hearing loss (1 paper, 2022). "The genes Elane, Pik3cd, and Il4r have also been previously associated with noise-induced and age-related hearing loss." (PMID 35454087, 2022).
Hepatic steatosis (1 paper, 2021). Steatosis is a term used to denote lipid accumulation within hepatocytes. "Protection from weight gain and improved glucose handling in IL-4Rα-deficient mice fed HF + HC diet, compared to WT controls, correlated with decreased hepatic steatosis." (PMID 34302121, 2021). "We show that IL-4Rα regulated HF + HC diet-driven weight gain, whole body adiposity, adipose tissue inflammatory gene expression, energy expenditure, locomotor activity, glucose metabolism, hepatic steatosis, hepatic inflammatory gene expression and hepatocellular damage." (PMID 34302121, 2021).
hookworm infection (1 paper, 2019). "IL-4Rα independent expression of RELM-α has been recently reported during hookworm infection, and was upregulated by Ym1, another molecule typically associated with alternative macrophage activation." (PMID 32039054, 2019).
Hyperkeratosis (1 paper, 2023). Hyperkeratosis is a histopathological term defining a thickened stratum corneum and may be present in many different skin conditions, with many possible overlaps. "However, after treating with anti-IL4Rα and ruxolitinib, hyperkeratosis and spongiosis were significantly restored." (PMID 37047166, 2023).
hyperreactivity (1 paper, 2014). "Like wild-type mice, IL-4R KO mice showed OVA-induced airway hyperreactivity which was further exacerbated by RV." (PMID 24907978, 2014).
Impaired glucose tolerance (1 paper, 2021). An abnormal resistance to glucose, i.e., a reduction in the ability to maintain glucose levels in the blood stream within normal limits following oral or intravenous administration of glucose. "HF diet-fed IL-4Rα-deficient mice, compared to WT controls, had increased fasting glucose and impaired glucose tolerance." (PMID 34302121, 2021).
Insulin resistance (1 paper, 2013). Increased resistance towards insulin, that is, diminished effectiveness of insulin in reducing blood glucose levels. "Otherwise, downstream of IL-4 receptor α (IL-4Rα) is the nuclear hormone receptor peroxisome proliferator-activated receptor γ (PPARγ), and when activated, it inhibits the expression of genes that promote inflammation and protects against insulin resistance." (PMID 23894289, 2013).
interstitial lung disease (1 paper, 2019). A diverse group of lung diseases that affect the lung parenchyma. "Previously shown significant difference of IL-4Rα BALF concentrations in EAA patients compared to other fibrotic interstitial lung diseases (namely IPF) strongly supports this hypothesis." (PMID 30911386, 2019).
kidney damage (1 paper, 2012). "Modulation of the IL4 pathway during ESRD may be due to an intracellular regulation involving different pathways but also could be possible that polymorphisms within the IL4R gene could alter the signalling pathway of IL-4, leading to a progression or prevention of kidney damage." (PMID 22817530, 2012).
leprosy (1 paper, 2016). Leprosy is a chronic infectious disease affecting primarily the skin and peripheral nervous system. "IL4R and IL21R both encode immunomodulatory cytokine that regulate adaptive immunity responses, which play important role in the leprosy development." (PMID 27976721, 2016). "The second suggestive association rs34411505 on 16p12.1 locates between IL4R and IL21R whose expressions were both elevated in the leprosy patients." (PMID 27976721, 2016).
listeriosis (1 paper, 2024). A bacterial infection caused by Listeria monocytogenes. "Overall, we provide a new perspective on the Treg-specific function of IL-4Rα signalling in listeriosis, highligting the importance of the stability and quality of Foxp3 Tregs." (PMID 39483462, 2024). "Here, we demonstrated that the deletion of IL-4Rα signalling on Tregs resulted in decreased Foxp3 Tregs and increased survival rates of mice in listeriosis." (PMID 39483462, 2024).
localized scleroderma (1 paper, 2025). Localized scleroderma is the skin localized form of scleroderma characterized by fibrosis of the skin causing cutaneous plaques or strips. "Dupilumab, a monoclonal antibody targeting the α subunit of the Interleukin-4 Receptor (IL-4Rα), blocks IL-4 and IL-13 signaling and has been proposed as a potential treatment for localized scleroderma." (PMID 40816240, 2025).
lung adenocarcinoma (1 paper, 2022). A carcinoma that arises from the lung and is characterized by the presence of malignant glandular epithelial cells. "Human lung adenocarcinoma cell line A549 endogenously expresses moderate levels of IL13Rα1 with no detectable IL13Rα2 or IL4Rα." (PMID 35939683, 2022).
meningioma (1 paper, 2021). A generally slow growing tumor attached to the dura mater. "In addition, the expression of IL4Rα and IL13Rα1 were increased in meningioma compared with normal brain tissue and were higher in invasive pituitary adenoma compared to non-invasive pituitary adenoma." (PMID 33419470, 2021).
metastasis (1 paper, 2019). The spread or migration of cancer cells from one part of the body (where they first appeared) to another. "This subgrouping for the co-expression patterns of IL4Rα and IL13Rα1 was significantly associated with age (p = 0.007), tumor size (p = 0.029), tumor stage (p = 0.027), and lymph node metastasis (p = 0.017), and significantly associated with CSS (Log-rank, p < 0.001)and RFS (Log-rank, p < 0.001)." (PMID 31540495, 2019).
muscle disorders (1 paper, 2023). "Since impairment of myoblast fusion causes several muscle disorders, the IL-4/IL-4Rα axis can be a potential therapeutic target for the treatment of muscular pathologies." (PMID 37174683, 2023).
Mycobacterium infection (1 paper, 2015). Infections with bacteria of the genus Mycobacterium. "Together, these data demonstrate that Arg1 is induced through an IL-4Rα-independent pathway and is only expressed after a well-established Mycobacterium infection in macrophage cell-specific IL-4Rα deficient mice." (PMID 25790379, 2015).
nail dystrophies (1 paper, 2026). "Dupilumab, an IL-4Rα antagonist, is effective for Th2-driven conditions, but its role in nail dystrophies has not been systematically assessed." (PMID 41948252, 2026).
Neurodevelopmental delay (1 paper, 2020). "By evaluating the association between fetal inflammation and neurodevelopmental delay at age 2, Clarke and collaborators have suggested that genetic alterations to the extracellular domain of IL4R may contribute to neurodevelopmental outcomes in pregnancies at high risk for preterm birth." (PMID 32499725, 2020).
neuropathy (1 paper, 2025). A disorder affecting the nervous system that manifests with pain, tingling, numbness, and/or muscle weakness. "Safety concerns, including the risk of accelerated disease progression seen with IL-4R blockade in some MF patients and the well-documented neuropathy associated with BV, raise the stakes for any combination approach." (PMID 40864740, 2025).
oral squamous cell carcinoma (1 paper, 2025). "Elevated expression of IL4Rα has been positively correlated with the recurrence of oral squamous cell carcinoma (OSCC) patients." (PMID 40656893, 2025).
Osteopenia (1 paper, 2022). Osteopenia is a term to define bone density that is not normal but also not as low as osteoporosis. "Deriving from exosomes of mesenchymal stem cells, miR-151-5p determined osteogenic versus adipogenic fate and rescued the osteopenia phenotype in Tsk/+ mice by inhibiting the IL-4Rα/mTOR pathway." (PMID 35464474, 2022). "Low levels of IL-4 or IL-4Rα can inhibit the fibrosis and osteopenia phenotypes." (PMID 35464474, 2022). "Prevented osteopenia, skin tighten and immune disorders by inhibiting the IL-4Rα/mTOR pathway." (PMID 35464474, 2022).
pancreatic (1 paper, 2024). "Moreover, higher levels of tumor accumulation of IL4R-Abx compared to Ctrl-Abx were observed up to 24 h after injection in Panc1 subcutaneous human pancreatic xenograft tumor." (PMID 38646639, 2024).
peritonitis (1 paper, 2022). Inflammation of the peritoneum (tissue that lines the abdominal wall and covers most of the organs in the abdomen). "Given the role of IL‐4Rα in the survival and regulation of circulating monocyte numbers in vivo, we next assessed if the observed decrease in monocytes impacts on their recruitment in a sterile peritonitis model." (PMID 36063138, 2022).
Pleural effusion (1 paper, 2022). The presence of an excessive amount of fluid in the pleural cavity. "Along with eosinophils, macrophages are the major infiltrates in pleural effusions in WT mice and are the main cells present in Il-4rα-/-/Il-5-/- mice." (PMID 36353644, 2022).